BRAF (B-Raf proto-oncogene, serine/threonine kinase)
Diseases named in the same sentence as BRAF in open-access papers (continued):
Sharing a sentence is not in itself a finding about the gene and the disease.
thyroid cancer (continued). "Although extensively implicated in thyroid cancer tumorigenesis and progression, the role of the BRAF V600E mutation in distant metastasis remains complex." (PMID 41306438, 2025). "The BRAF V600E mutation has emerged as a central driver in the molecular landscape of thyroid cancer, particularly PTC." (PMID 41368991, 2025). "BRAF (B-type Raf kinase) gene alterations have been described in many tumor types and are among the most common genetic mutations in thyroid cancer, particularly papillary thyroid carcinoma (PTC)." (PMID 40075589, 2025). "A pooled analysis of 29 studies on sporadic adult thyroid cancer reported an overall BRAF mutation prevalence of 44% in papillary thyroid cancer (PTC) and 24% in anaplastic thyroid carcinoma (ATC)." (PMID 40332392, 2025). "The genetic mutations associated with the development of MSO are similar to those found in thyroid gland cancer, with the BRAF (V600E) mutation present in about two-thirds of cases." (PMID 40385882, 2025). "Studies have confirmed the importance of the detection of BRAF gene mutations in the diagnosis, treatment and determination of prognosis of thyroid cancer." (PMID 40963858, 2025). "BRAF mutations in primary thyroid cancer predict a poorer prognosis, but studies in malignant struma ovarii show they do not always correlate with poor outcomes." (PMID 40746588, 2025). "The relationship between the BRAF V600E mutation and aggressive clinicopathological features in thyroid cancer, particularly in MPTC, remains a subject of debate, with studies reporting mixed findings." (PMID 40805249, 2025). "Type I mutant-BRAF is the most prevalent mutation in thyroid cancer, occurring at the V600 position (e.g., V600E, V600K, V600D, V600R and V600M)." (PMID 40063000, 2025). "The BRAF V600E mutation, which is identified in approximately 80% of PTCs and 50% of ATCs in Japanese patients with thyroid cancer, drives tumorigenesis via MAPK pathway activation." (PMID 40844731, 2025). "The BRAF V600E mutation plays a central role in modulating therapeutic response in thyroid cancers, notably by activating the MAPK pathway, which suppresses key proteins involved in iodine uptake, such as the sodium–iodide symporter and the TSH receptor." (PMID 40332392, 2025). "Our data showed that while mannose alone did not influence cell apoptosis, it significantly increased PLX4032-induced apoptosis in BRAF-mutated thyroid cancer cells." (PMID 40063000, 2025). "In thyroid cancer, mutations in BRAF, particularly the V600E mutation, can lead to resistance to BRAF inhibitors and anaplastic transformation." (PMID 40129883, 2025). "The mechanisms of resistance to BRAF inhibitors in thyroid cancer include PIK3CA mutations that hyperactivate ERK when BRAF is inhibited." (PMID 40129883, 2025). "We should remark the importance of BRAF mutations providing opportunities for targeted drug therapy in thyroid cancer." (PMID 39744583, 2025). "The evolving molecular genetic profile of thyroid cancer, including mutations in genes like BRAF and RAS, indicates the emergence of new etiologies for this tumor type, possibly of a chemical or dietary nature." (PMID 41029555, 2025). "The MAPK signaling pathway serves as a principal pathway in the development and progression of thyroid carcinoma, primarily activated through mutations in the BRAF and RAS genes." (PMID 41462994, 2025). "The somatic BRAF V600E (c.1799T>A) mutation shows 100% specificity for thyroid carcinoma, which eliminates some secondary surgery for ITNs." (PMID 40093750, 2025). "Especially, radioiodine‐refractory thyroid carcinomas with BRAF V600E mutation, yielding a response rate of 48% and a progression‐free survival of 15.1 months." (PMID 39950095, 2025).
thyroid cancer (continued). "Studies have shown that thyroid carcinomas bearing BRAF mutations are less sensitive to BRAF inhibitors and can develop primary or acquired resistance due to mutational events or the activation of alternative pathways." (PMID 40129883, 2025). "TERT promoter mutations are common in various cancers, including thyroid carcinomas, where they enhance the proliferative potential of BRAF—or RAS-driven clones." (PMID 40149275, 2025). "A review of BRAF mutation detection methods in various non-thyroid carcinomas indicated NGS had a sensitivity of 98.6% and specificity of 100%." (PMID 41562808, 2025). "In this study, we aim to explore the correlation between these critical biological markers—BRAF V600E mutation, thyroglobulin, and calcitonin—and the prognosis of thyroid cancer." (PMID 39767732, 2024). "Papillary thyroid carcinoma (PTC) is the most frequent type of thyroid cancer, and the BRAF V600E mutation is the most frequent genetic mutation in PTC." (PMID 38607456, 2024). "Current literature and previous studies have similarly demonstrated an association between the BRAF mutation and advanced stages of thyroid cancer." (PMID 39767732, 2024). "In thyroid cancer, the BRAF V600E mutation leads to constitutive activation of the RAF/ERK pathway and consequent deactivation of thyroid-specific genes resulting in dedifferentiation and tumor progression." (PMID 38275291, 2024). "Approximately 8% of all human cancers harbour the mutated BRAF gene, and BRAF V600E mutation is the most common genetic alteration in thyroid cancers within the MAPK signalling pathway." (PMID 38203733, 2024). "The BRAF V600E mutation is effectively the sole molecular marker used to predict thyroid cancer in clinical settings." (PMID 39768693, 2024). "While mutations in BRAF are common in thyroid cancer, advanced PTC patients currently lack therapeutic options targeting the MAPK pathway, and despite the approved combination of BRAF and MEK1/2 inhibition for BRAF-mutant ATC, resistance often occurs." (PMID 38521968, 2024). "While early studies of BRAF inhibitors demonstrated anti-tumor activity in advanced thyroid cancers harboring the BRAF V600E mutation, subsequent experience and research showed limited long-term disease control due to abundant compensatory mechanisms." (PMID 38275291, 2024). "A number of case reports or case series for neoadjuvant purposes have been published in different pathological types of thyroid cancer, such as BRAF V600E–mutated anaplastic thyroid carcinoma and medullary thyroid cancer with RET mutation." (PMID 39071474, 2024). "In contrast, BRAF-like mutations, including the BRAF V600E mutation, are commonly linked to more aggressive thyroid cancers, characterized by elevated MAPK signaling and a reduced sensitivity to negative feedback." (PMID 39766147, 2024). "The combination of BRAF mutation with other gene mutations significantly increases the risk of thyroid cancer invading the thyroid membrane and recurrence, with TERT mutations being the most common co-occurring mutation." (PMID 38607456, 2024). "A study based on 458 Chinese patients with thyroid cancer reported that the prevalence of BRAF driver mutations is 76.0%, followed by RET rearrangements (7.6%), while the prevalence of RAS mutations is only 4.1%." (PMID 39600648, 2024). "Among the genes associated with thyroid cancer BRAF, RAS, KRAS, NRAS, PTEN, and PRKAR1A genes participate in regulating oxidative metabolism." (PMID 39180118, 2024). "Several studies demonstrated the association between the BRAF V600E mutation with adverse clinicopathologic features and poor outcomes in tumors such as colorectal and thyroid cancers." (PMID 38919805, 2024). "The BRAF V600E mutation was detected in the postoperative pathological specimens of 252 patients with thyroid cancer included in this study." (PMID 38607590, 2024). "first reported the presence of BRAF mutations in 35.8% (28/78) of differentiated thyroid cancers in 2003." (PMID 39529955, 2024).
thyroid cancer (continued). "The substitution of glutamic acid for valine at codon 600 (V600E) is the most common BRAF mutation linked to thyroid cancer." (PMID 38501105, 2024). "The BRAF mutation is a critical genetic modification in the landscape of thyroid cancer, notably in PTC." (PMID 38501105, 2024). "In clinical tissue studies, colon cancer and thyroid cancer patients with the BRAF(V600E) mutation showed elevated CTHRC1 expression and immune cell infiltration." (PMID 39052013, 2024). "Previous research indicating an increased risk of papillary thyroid carcinoma with BRAF mutation in individuals with a high BMI suggests an independent relationship between obesity and thyroid cancer, which is clinically significant." (PMID 39767732, 2024). "Comprehending the molecular details of the BRAF mutation has improved our understanding of the biology of thyroid cancer and opened the door to tailored treatment approaches." (PMID 38501105, 2024). "As oncogenic BRAF mutations are commonly found in thyroid cancers, the blockade of the associated signaling pathway (ERK1/2, overactivated by mutation) proved a clear rationale." (PMID 39064466, 2024). "This study examines the relationship between biological markers—BRAF V600E mutation, thyroglobulin (Tg), and calcitonin—and thyroid cancer prognosis." (PMID 39767732, 2024). "A significant association was found between BRAF V600E mutation AF and thyroid cancer recurrence (p = 0.023, OR = 10.080, OR (95%CI) = 1.010–1.154)." (PMID 38607456, 2024). "Before PSM, the BRAF V600E mutation was detected in postoperative pathological specimens from 252 patients with thyroid cancer, of which 73.0% (184/252) were the mutant type and 27% (68/252) were the wild type." (PMID 38607590, 2024). "A case report in 2022 described a 77-year-old man with diagnosis of metastatic differentiated thyroid cancer and evidence of presence of mutation of BRAF K601E on liquid biopsy was treated with sorafenib, showing a good response to the treatment." (PMID 38758843, 2024). "BRAF V600E is the most common mutation in thyroid cancer, occurring in approximately 60% of papillary thyroid carcinomas (PTC)." (PMID 39135992, 2024). "With the development of oncogene diagnosis, the BRAF V600E gene mutation is considered to be related to extracapsular invasion, lymph node metastasis, multifocality and therapeutic efficacy of thyroid cancer." (PMID 38607590, 2024). "Our in silico results support that USPs, other than USP42, are altered in sporadic thyroid cancer, and that USPs can be in line with other mutations associated with thyroid cancer development, such as BRAF p.(Val600Glu)." (PMID 38338801, 2024). "Further research will be required to determine the optimal activity for different subgroups within intermediate- and high-risk thyroid cancer, in particular considering responses in the context of molecular profile (e.g. BRAF mutated vs RAS mutated)." (PMID 39283868, 2024). "Blockade of ERK signaling by BRAF inhibitor inactivates ERK-dependent feedback, and then reactivates multiple RTKs and their downstream ERK and AKT signaling cascades, thereby causing the resistance of BRAF-mutant thyroid cancer cells to BRAF inhibitor." (PMID 38795180, 2024). "Nevertheless, even considering the high discrepancy in percentage of BRAF V600E mutated samples, this point mutation is considered a hallmark of thyroid cancer, especially characteristic for its papillary variant." (PMID 38203733, 2024). "Simultaneously, several studies have emphasized that the incidence of lymph node and distant metastasis in thyroid cancer exhibiting BRAF gene mutations is notably low, suggestive of a potential protective mechanism." (PMID 39558959, 2024).
thyroid cancer (continued). "Comparably, pharmacological inhibition of BRAF or ERK1/2 also significantly down-regulated USP15 expressions in BRAFV600E-mutated human thyroid cancer cells." (PMID 38750011, 2024). "Comparing molecular testing for key mutations of thyroid cancer, such as BRAF V600E and RET, is important among Hispanics and other races/ethnicities and within Hispanic subgroups." (PMID 38539437, 2024). "These are indicated for treating BRAF mutation cancers, including unresectable or metastatic cutaneous melanoma, metastatic non-small-cell lung cancer, metastatic anaplastic, thyroid cancer, and metastatic colorectal cancer." (PMID 38254833, 2024). "When the frequency of the BRAF V600E mutation is greater than 28.2%, the risk of thyroid cancer recurrence increases sixfold compared to when the frequency is 28.2% or lower." (PMID 38607456, 2024). "We provide compelling evidence that CTHRC1 is linked to the BRAF(V600E) mutation in both colon and thyroid cancers, further highlighting the significant role of CTHRC1 in influencing patient prognosis." (PMID 39052013, 2024). "Treatment for thyroid cancer has changed dramatically with the introduction of targeted medications intended to block the effects of the BRAF V600E mutation." (PMID 38501105, 2024). "Research indicates that TERT mutation is infrequent in children and teenagers, while combined with BRAF mutation, they contribute to increased malignancy in thyroid cancer." (PMID 38607456, 2024). "The most common somatic mutation found in adult thyroid cancer is harbored in the BRAF gene, i.e., the BRAFV600E mutation." (PMID 39420942, 2024). "A total of eighteen studies identified mutations in the thyroid cancer driver gene BRAF V600E, with a collective sample seven hundred and seventy-one patients." (PMID 38904052, 2024). "ctDNA analysis can detect prevalent genetic abnormalities in thyroid cancer, such as BRAF and RAS mutations and RET/PTC rearrangements." (PMID 38501105, 2024). "Our study does not support the idea that obesity significantly influences the presence of the BRAF mutation in thyroid cancer." (PMID 39767732, 2024). "Trametinib is currently approved for various cancers with BRAF mutations, such as non-small cell lung cancer and thyroid cancer, either as monotherapy or in combination with dabrafenib, a BRAF inhibitor, for improved therapeutic efficacy." (PMID 38473413, 2024). "To summarize, BRAF inhibitors are an effective targeted treatment for particular subtypes of thyroid carcinoma with BRAF mutations." (PMID 38501105, 2024). "These inhibitors are especially important for malignancies with specific BRAF mutations, such as thyroid carcinoma." (PMID 38501105, 2024). "We observed that BRAF mutations led to change in the expression level of 7 targets most prominently in thyroid carcinoma (THCA)." (PMID 39186767, 2024). "The analysis of the BRAF mutation has emerged as a significant advancement in the molecular diagnosis of thyroid carcinoma in recent years, garnering extensive research attention." (PMID 38509485, 2024). "Biomarkers such as thyroglobulin (TG), calcitonin, and BRAF V600E mutations play distinct roles in diagnosing and prognosis thyroid carcinoma subtypes." (PMID 39767732, 2024). "Consistent with prior analyses, the previously identified mutations with described roles in BRAF inhibitor resistance were markedly more prevalent in de-differentiated thyroid carcinoma histologies." (PMID 38275291, 2024). "The percentage of reported thyroid carcinoma cases with a mutated BRAF gene mainly depends on the studied population." (PMID 38203733, 2024). "Although BRAFV600E represents 95% of all BRAF mutations, uncommon BRAF mutations have been reported in thyroid carcinomas and represent an alternative mechanism of BRAF activation with unclear clinical significance." (PMID 38532782, 2024).
thyroid cancer (continued). "Three patients had an NRAS mutation, two with FTC and one with a poorly differentiated thyroid carcinoma, and three patients had a BRAF V600E mutation and PTC." (PMID 39685478, 2024). "Hashimoto’s thyroiditis and BRAF-mutation are protective and risk factors for thyroid cancer aggressiveness, respectively." (PMID 37190300, 2023). "The objective of this study was to explore the correlation between the BRAF V600E mutation AF and histopathological features of thyroid cancer." (PMID 38201541, 2023). "Thyroid cancer is another tumor type with a high mutation positivity rate of 74% with BRAF at 40% followed by RET at 17.3%." (PMID 37483495, 2023). "Our findings revealed the hsa-miR-125b expression changes in thyroid cancer invasion, in BRAF V600E mutant tumors and in intermediate recurrence risk." (PMID 36980957, 2023). "Recent meta-analyses have revealed that thyroid cancers with concurrent BRAF V600E or RAS and TERT promoter mutations were associated with increased tumor aggressiveness compared to those harboring BRAF V600E, RAS, or TERT promoter mutations alone." (PMID 36672362, 2023). "In a meta-analysis, the overall prevalence of the BRAF mutation in thyroid cancer was found to be 45%." (PMID 36975440, 2023). "Molecular testing, such as that for the BRAF V600E mutation, has been suggested to distinguish aggressive PTCs; the BRAF V600E mutation accounts for 60% of mutations in thyroid cancer." (PMID 37158852, 2023). "Genetic alterations in thyroid cancer have been well characterized in the literature, with hundreds of genetic driver mutations having been identified, the most common ones being BRAF V600E and RAS point mutations." (PMID 38201541, 2023). "Dabrafenib plus Trametinib currently only have tumor agnostic approval in the USA for patients with BRAF V600E mutations, including thyroid cancer." (PMID 38255638, 2023). "In this study, we demonstrate that DSF/Cu can kill BRAFV600E-mutated thyroid cancer cells and improves their cellular response to BRAF kinase inhibitor by relieving feedback activation of MAPK/ERK and PI3K/AKT pathways in an ROS-dependent manner." (PMID 36834830, 2023). "Thyroid cancers with BRAF mutations and ROS1 fusion resulted in the highest frequency of recommendations." (PMID 36251535, 2023). "Papillary thyroid cancer (PTC), which is often driven by acquired somatic mutations in BRAF genes, is the most common pathologic type of thyroid cancer." (PMID 36624452, 2023). "Further study demonstrated that combination of HER inhibitor to BRAF/MEK inhibitor overcomes resistance to vemurafenib in BRAF mutated thyroid cancer cells." (PMID 36624452, 2023). "Contrary to BRAF V600E, which is 100% specific to thyroid cancer, the specificity of RAS mutations ranges from 74 to 88%." (PMID 37374164, 2023). "Two studies found a potential therapeutic role for vitamin C in thyroid cancer patients with BRAF V600 E mutation as vitamin C has antitumour effects and can kill cancer cells by MAPK/ERK and PI3K/AKT pathways." (PMID 37246589, 2023). "The BRAF V600E mutation and DNA promoter methylation play important roles in the pathogenesis of thyroid cancer (TC)." (PMID 36975440, 2023). "This is in line with studies that have shown how BRAF mutations are more frequent in aggressive thyroid cancer subtypes." (PMID 38076095, 2023). "BRAF mutation is a commonly mutated oncogene in thyroid cancer associated with advanced tumor progression and decreased 10-year survival." (PMID 37190300, 2023). "For instance, a study exposing BRAF V600E mutated KTC1 thyroid cancer cells to long term vemurafenib showed development of secondary KRAS point mutations, allowing these cells to bypass BRAF inhibition." (PMID 37435488, 2023).